CASP6 (caspase 6)
Diseases named in the same sentence as CASP6 in open-access papers (continued):
Sharing a sentence is not in itself a finding about the gene and the disease.
neurodegenerative disease (22 papers, 2012 to 2026). A disorder of the central nervous system characterized by gradual and progressive loss of neural tissue and neurologic function. "Pleiotrophin deletion upregulates caspase 6, which is associated with axonal degeneration and neurodegenerative diseases, and the deleterious effects produced can be partially compensated for by the simultaneous induction of the neuroprotective gene MGST3." (PMID 39000460, 2024). "Caspase-6 is an important drug target that is implicated in various neurodegenerative diseases, yet the availability of tools to monitor caspase-6 activity in a cellular context is limited." (PMID 22253931, 2012). "Finally, caspase-6 has been uniquely implicated in neurodegenerative diseases such as Alzheimer’s and Huntington’s, where excessive caspase-6 activity and elevated levels correlate with axonal degeneration and neuropathological lesions." (PMID 41227316, 2025). "Caspase-6 also cleaves α-tubulin, destabilizing microtubules and contributing to neurodegenerative disease." (PMID 41363857, 2026). "Casp-6’s involvement in neurodegenerative diseases has positioned it as a target for synthetic inhibitors as well." (PMID 41270077, 2025). "This approachand the new tools described will enable rigorous interrogation ofthe role of caspase-6 in developmental biology and in inflammatoryand neurodegenerative diseases." (PMID 37104712, 2023). "Due to their potential in the treatment of neurodegenerative diseases, caspase-6 inhibitors have attracted widespread attention." (PMID 34959651, 2021). "Due to the potencies in the treatment of neurodegenerative diseases, caspase-6 inhibitors have attracted intensive attention." (PMID 34959651, 2021). "This is unique from its role in neurodegenerative diseases or other inflammatory responses, during which the catalytic activity of caspase-6 is required for the proteolytic activation of its substrates to execute its non-apoptotic function." (PMID 33426542, 2020). "Caspase-6 plays crucial roles in several neurodegenerative diseases, including Huntington’s disease, Alzheimer’s disease, and Parkinson’s disease." (PMID 33426542, 2020). "Caspase-6 (C6) is one such protease known for its role as a pro-apoptotic executioner caspase and its aberrant activity in several neurodegenerative diseases." (PMID 29560279, 2018). "For instance, numerous studies point at a critical role of caspase-6 in the development of neurodegenerative diseases." (PMID 28659495, 2017). "Inhibition of caspase-6 is a potential therapeutic strategy for some neurodegenerative diseases, but it has been difficult to develop selective inhibitors against caspases." (PMID 23227217, 2012). "With recent data implicating caspase-6 as an important mediator of neurodegenerative diseases, the assay described here enables drug discovery efforts to characterize cell-active inhibitors of this target." (PMID 22253931, 2012). "Accumulated evidence has suggested that the activation of caspase-6 is responsible for neuronal apoptosis and amyloid β peptide (Aβ) deposition, which is highly involved in age-dependent axon degeneration and neurodegenerative diseases, such as Huntington’s disease and Alzheimer’s disease." (PMID 34959651, 2021). "As SMSr constitutes the principle CPE synthase in brain, it would be of interest to explore whether its proteolytic cleavage by caspase-6 has any relevance in the pathogenesis of neurodegenerative diseases." (PMID 28659495, 2017). "However, with the increasing number of research groups focusing on Casp6 as a therapeutic target against neurodegenerative diseases, the possibility that Casp6 inhibitors will one day reach human trials is promising." (PMID 28241839, 2017). "Caspase-6 inhibitors could be useful against these neurodegenerative diseases but most Caspase-6 inhibitors have been exclusively studied in vitro or show acute liver toxicity in humans." (PMID 28241839, 2017).
neurodegenerative disease (continued). "Together, these findings suggest that inhibition of Casp6 might be an efficient therapeutic approach against neurodegenerative diseases including cognitive decline in aged and AD individuals." (PMID 25470254, 2014). "Our results suggest that inhibitors of Casp6 could be considered as novel therapeutic approaches for neurodegenerative diseases without a high risk of carcinogenic side-effects." (PMID 25470254, 2014). "Other proteins central to neurodegenerative diseases, such as APP, presenilin, and tau in AD are also substrates for caspase-6." (PMID 26505998, 2015).
infection (18 papers, 2016 to 2025). The state of being infected such as from the introduction of a foreign agent such as serum, vaccine, antigenic substance or organism. "In addition, Lamin A, a marker for caspase-6 activation, was cleaved as well after EV-A71 infection, which was apparently associated to nuclear dysregulation and subsequent cell death." (PMID 33481814, 2021). "After infection, the cells were cultured overnight, and the quantities of viral nucleocapsid protein and caspase-6 were analysed by Western blot." (PMID 40920846, 2025). "Caspase-6 (CASP6) mediates innate immunity and inflammasome activation in response to apoptosis caused by pathogen infection." (PMID 38393075, 2024). "qRT-PCR confirmed that caspase-3 and caspase-6 expression was reduced during SH-SY5Y cell infection with the ΔbimA mutant." (PMID 37409935, 2023). "Casp6–/– mice developed more severe skin lesions than WT mice, especially on days 8 and 10 post-infection (dpi)." (PMID 36146839, 2022). "We observed that the HSV-1 ΔUs3 strain induced minimal skin lesions in both WT and Casp6–/– mice, all of which survived the infection." (PMID 36146839, 2022). "Our findings suggest that CASP6 has a critical role during infection, in contrast to it being dispensable during LPS transfection." (PMID 34740613, 2021). "Similar strategies can be employed to investigate the PANoptosome components that are induced by IAV throughout the timeline of infection to study the role of caspase-6 and other molecules at different infection phases." (PMID 33426542, 2020). "For this reason we checked the mRNA cytokine expression levels at a time when the bacterial load was comparable among WT and caspase-6-/- mice (6 h post infection)." (PMID 28686630, 2017). "Expression of the IL-10 gene was also increased in caspase-6-/- mice as early as 6 hours after infection." (PMID 28686630, 2017). "Together, this is the first report addressing the role of caspase-6 for in vivo resistance in a defined infection model." (PMID 28686630, 2017). "Casp6 acts as executioner caspase and is likely to prevent GI cell apoptosis, while the increased Lysozyme1 expression can prevent infection and inflammation development." (PMID 27449294, 2016). "However, upon infection with Salmonella, both Gsdmd–/–;Bid–/–;Mlkl–/–;Casp3–/–;Casp7–/–;Casp9–/– and Gsdmd–/–;Bid–/–;Mlkl–/–;Casp3–/–;Casp6–/–;Casp7–/–;Casp9–/– iBMDMs underwent substantial cell death, although this was delayed compared to WT iBMDMs." (PMID 32735843, 2020). "Furthermore, caspase-6 was critically involved in the host defense against IAV infection in a murine model, and Casp6−/− mice were more likely to succumb to infection and had a higher viral burden." (PMID 33426542, 2020). "Following infection, the genes CASP6 and IRF7 were upregulated by greater than twofold." (PMID 31462004, 2019). "Some reports describe that caspase-6 is activated during infection with various pathogens in vitro." (PMID 28686630, 2017). "Thus, caspase-6 clearly contributes to in vivo resistance against B. pseudomallei in an early stage of the infection." (PMID 28686630, 2017). "Whereas the knowledge about the role of caspase-6 in infectious diseases is very limited, the impact of the pro-inflammatory caspase-1, a component of the inflammasome, has been intensively studied in various infection models." (PMID 28686630, 2017). "Thus, caspase-6 seems to affect the expression of IL-10 and IL-1β in a very early stage after infection." (PMID 28686630, 2017). "Absence of caspase-6 was associated with significantly increased mRNA expression levels of two cytokines in a very early stage after infection, the anti-inflammatory IL-10 and the pro-inflammatory IL-1β, that are marker of poor disease outcome." (PMID 28686630, 2017). "Therefore, an apoptosis-inducing HSV-1 strain may accentuate the role of caspase-6 during infection." (PMID 36146839, 2022).
infection (continued). "The relative contributions of caspase-6 and caspase-8 to cell death during WT EMCV infection will be a subject for future work." (PMID 39928567, 2025). "Specifically, in the death receptor-mediated apoptosis signaling pathway, downregulation of TNFα, TRAIL, CASP6, and CASP8 was observed, while several genes in the autophagy and mitophagy pathways showed upregulated expression post-infection." (PMID 39650642, 2024). "In the early infection stage, the Spodoptera exigua host cells had high membrane permeability and cleaved gasdermin D (GSDMD) but uncleaved Casp-6 (SeCasp-6)." (PMID 36744941, 2023). "To test the role of caspase-6 more thoroughly on HSV-1 infection, we used the footpad infection model." (PMID 36146839, 2022). "Caspase-6 induces the cleavage of caspase-8 to form a positive feedback loop, promoting intrinsic apoptosis; increased caspase-8 and caspase-9 cleavage have both been reported in WT EMCV infections." (PMID 39928567, 2025). "The loss of apoptotic caspases has previously been shown to increase the expression of type I IFNs, and indeed, we detected increased type I IFN expression in Casp6−/− BMDMs upon infection with gram-negative bacteria." (PMID 34740613, 2021). "Here, we report that the understudied caspase-6 (CASP6) contributes to the activation of the CASP11-NLRP3 inflammasome in response to infections with gram-negative bacteria." (PMID 34740613, 2021). "We here examined the impact of caspase-6 in an in vivo infection model using the Gram-negative rod Burkholderia pseudomallei, causing the infectious disease melioidosis that is endemic in tropical and subtropical areas around the world." (PMID 28686630, 2017). "It is therefore highly conceivable that the activation of caspase-6 (and presumably, subsequent caspase-8 activation) promotes the activation of caspase-3, increasing the efficiency of the caspase-3-dependent, GSDME-mediated cell lysis observed during WT EMCV infection." (PMID 39928567, 2025). "Our findings here demonstrate that CASP6 can regulate CASP11 activation to mediate the activity of the CASP11-NLRP3 inflammasome, cytokine release, and cell death, further extending our understanding of the biological roles of this mysterious caspase in infection and disease." (PMID 34740613, 2021). "Notably, the moribund WT and Casp6–/– mice all had enlarged intestines, consistent with previous publications in WT mice, where it was speculated that DRG infection resulted in descending infection from the DRG to the intestines as well as the skin." (PMID 36146839, 2022). "Thus, whether caspase-6 plays a role for determining resistance against microbial pathogens has not been addressed in any defined in vivo infection model yet." (PMID 28686630, 2017). "During the infection, we also observed increased production of IL-1β in turbot, however, no mature IL-1β was detected, suggesting that CASP3/7 and CASP6 may not be involved in processing pro-IL-1β." (PMID 35610210, 2022).
liver (3 papers, 2014 to 2023). "First, hepatic Caspase 6 expression and liver function were determined in patients undergoing hepatectomy and mice liver IR model." (PMID 37828624, 2023). "However, the potential regulation of RIPK1 by Caspase 6 in liver IR model is virtually unexplored." (PMID 37828624, 2023). "Our findings underscore a novel mechanism of Caspase 6 mediated RIPK1-IκBα interaction in regulating macrophage NEK7/NLRP3 function and hepatocytes ferroptosis, which provides therapeutic targets for clinical liver IR injury." (PMID 37828624, 2023).
neurological disorders (3 papers, 2016 to 2025). "Despite the classification of caspase-6 as an apoptotic caspase and the knowledge of its association with neurological disorders, the functions and importance of caspase-6 in innate immunity have remained largely a mystery." (PMID 33426542, 2020).
bacterial infection (2 papers, 2019 to 2023). "In our study, we found that caspase-6 was mainly distributed in the mucosa layers and was induced by bacterial infection." (PMID 36974664, 2023).
infectious disease (1 paper, 2017). A disorder directly resulting from the presence and activity of a microbial, viral, or parasitic agent in humans. "But although caspase-6 is known to have a function in controlling immunological processes, its role in infectious diseases has rarely been addressed." (PMID 28686630, 2017).
CASP6 also shares sentences with these, for which no sentence is quoted: atherosclerosis (2 papers); inflammation (2); multiple myeloma (2); Parkinson's (2); triple-negative breast carcinoma (2); angiosarcoma (1); bone cancer (1); cerebral amyloid angiopathy (1); colon (1); depression (1); Down syndrome (1); follicular lymphoma (1); frontotemporal dementia (1); glaucoma (1); HCMV infection (1); head and neck squamous cell carcinoma (1); hippocampal atrophy (1); Hyperglycemia (1); Insulin resistance (1); ischemic stroke (1); liver disease (1); liver failure (1); microcephaly (1); Morquio disease (1); neurodevelopmental disorder (1); optic neuropathies (1); pancreatic adenocarcinoma (1); periodontitis (1); peritonitis (1); polycystic ovary syndrome (1).
A further 13 diseases each share a sentence with CASP6 in 1 paper.